ALB (albumin)
Diseases named in the same sentence as ALB in open-access papers (continued):
Sharing a sentence is not in itself a finding about the gene and the disease.
prediabetes (29 papers, 2013 to 2026). "The risk of developing prediabetes (impared fasting glucose or hemoglobin A1c) was analyzed according to baseline and percent change in serum albumin concentration using Cox regression analysis." (PMID 28430803, 2017). "However, higher percent change in serum albumin levels was still significantly associatied with decreasing risk of new-onset prediabetes in the multivariate Cox regression models (models 1–5), even when baseline BMI and BMI change were concurrently adjusted." (PMID 28430803, 2017). "However, a higher percent change in serum albumin was significantly associated with decreasing risk of incident prediabetes in crude and multivariate Cox regression models (models 1–5) as both quartiles and continuous values." (PMID 28430803, 2017). "However, inverse associations were found between serum albumin measured at prediabetes diagnosis and fasting glucose (standardized β = -0.043, p < 0.001) or HbA1c measured at prediabetes diagnosis (standardized β = -0.213, p < 0.001)." (PMID 28430803, 2017). "This is a post hoc analysis of urinary albumin-to-creatinine ratio (uACR) within the normoalbuminuric range in relation to cardiometabolic risk factors among initially normoglycemic, normotensive participants in the Pathobiology of Prediabetes in a Biracial Cohort (POP-ABC) Study." (PMID 38233076, 2024). "Herein, we sought to investigate whether baseline and change in serum albumin levels during an observation period could be independent risk factors for prediabetes especially impaired fasting glucose (IFG) or hemoglobin A1c (IA1c) in subjects without baseline and new MetS." (PMID 28430803, 2017). "In fact, glycated albumin has been shown to complement glycated hemoglobin as a marker of prediabetes." (PMID 38741158, 2024). "In both groups, healthy and prediabetes, there was a decrease in glycated albumin for 14 days of treatment." (PMID 35075363, 2022). "Blood samples were drawn and used for the analysis of the FBG and fasting insulin levels and glycated albumin to define prediabetes criteria before hematology analysis." (PMID 35497944, 2022). "Additional findings:HbA1c detected ≤50% of African immigrants with prediabetes.HbA1c combined with the glycated albumin test increases sensitivity to 80% for diagnosing prediabetes." (PMID 33705304, 2021). "Regardless of baseline BMI and BMI change, the subjects with incident prediabetes showed significantly lower percent change in serum albumin level, compared to normal subjects." (PMID 28430803, 2017). "The AUC of serum albumin change was significantly larger than those for age, BMI and fasting glucose for predicting prediabetes development (all p < 0.001)." (PMID 28430803, 2017). "Hazard ratios and 95% confidence intervals for prediabetes development according to baseline and percent changes in serum albumin." (PMID 28430803, 2017). "The hazard ratio for incident prediabetes decreased as percent change in serum albumin concentration (quartiles and per 1%) increased in a crude and fully adjusted model." (PMID 28430803, 2017). "We recommend periodic evaluation of urine albumin in addition to HbA1C in patients with prediabetes conditions." (PMID 23841037, 2013). "Besides, prediabetes might have an early renal lesion, such as the thickening of glomerular basement membrane, and it was an independent risk factor for glomerular hyperfiltration and could increase urinary albumin creatinine ratio (uACR), contributing to a poor kidney prognosis." (PMID 32398098, 2020). "Although baseline serum albumin levels were not different, serum albumin levels measured before and after prediabetes diagnosis showed a distinct pattern among the three groups: Serum albumin levels kept increasing drastically until the end of follow-up in the regression group." (PMID 28430803, 2017). "We sought to investigate whether baseline serum albumin and change in serum albumin could be independent risk factors for prediabetes in subjects without MetS." (PMID 28430803, 2017).
prediabetes (continued). "Although the significance of percent change in serum albumin levels for predicting prediabetes did not surpass that of HbA1c which was the strongest glycemic parameter, change in serum albumin was a more significant risk factor for impaired glucose control compared to fasting glucose or BMI." (PMID 28430803, 2017). "In this study, we showed that there is a close association between the plasma glucose level and urinary excretion of albumin in the general population, suggesting that even prediabetes may play a possible role in the pathogenesis of microvascular complications." (PMID 28158221, 2017). "There is no definite prediabetes cut-off level for glycated albumin, but one study used a level of ≥13.35 %, corresponding to an HbA1c level of 5.7 % (39 mmol/mol) to detect prediabetes." (PMID 39091901, 2024). "In the present study, we found a negative correlation between WBCs and glycated albumin in the prediabetes rats." (PMID 35497944, 2022). "Percent change in serum albumin was also apparently higher in subjects without incident prediabetes (4.77 ± 6.20 vs 1.42 ± 6.31%, p < 0.001)." (PMID 28430803, 2017). "Change in serum albumin was higher in the BMI increasing group regardless of prediabetes development." (PMID 28430803, 2017). "Then, serum albumin levels increased only in the stationary group at the end of follow-up while the progression group had no changes after prediabetes diagnosis." (PMID 28430803, 2017). "However, increase in serum albumin concentrations was protective against prediabetes development, regardless of baseline BMI, BMI change, or insulin resistant status." (PMID 28430803, 2017). "Conversely, serum albumin levels did not increase until one year before prediabetes diagnosis in the stationary and progression groups, and then increased slightly at the time of prediabetes diagnosis." (PMID 28430803, 2017). "Although serum albumin change’s predictive power for diagnosing prediabetes could not surpass that of HbA1c, it was stronger than those of fasting glucose, BMI, and age." (PMID 28430803, 2017). "Besides, the records of glycated albumin were lacking, and this parameter may serve as a better indicator for screening prediabetes." (PMID 32398098, 2020).
intracerebral hemorrhage (28 papers, 2012 to 2026). A cerebrovascular disorder characterized by bleeding into one or both cerebral hemispheres including the basal ganglia and the cerebral cortex. "In particular, systemic infection—a common complication in patients with intracerebral hemorrhage—can independently increase lactate dehydrogenase levels and decrease serum albumin, potentially confounding the observed association between LAR and AKI." (PMID 41487425, 2025). "Of these proteins, both albumin and thrombin have been implicated in pathophysiologic processes including epileptogenesis and intracerebral hemorrhage." (PMID 22507553, 2012). "Creatinine-to-albumin ratio can serve as an independent and superior predictor of mortality and complications in intracerebral hemorrhage patients." (PMID 40843261, 2025). "While creatinine and albumin levels have been studied individually, the prognostic value of the creatinine-to-albumin ratio in predicting mortality in intracerebral hemorrhage patients remains underexplored." (PMID 40843261, 2025). "The BUN to Albumin Ratio (BAR) has been associated with AKI and hospital mortality in ICU patients with intracerebral hemorrhage, emphasizing the utility of simple laboratory ratios." (PMID 41425961, 2025). "The association between fibrinogen-to-albumin ratio (FAR) and in-hospital mortality in patients with spontaneous intracerebral hemorrhage (ICH) has been established." (PMID 39099785, 2024). "Using K-means and cluster analysis, we identified potential risk factors for anticoagulant use in the exploratory cohort, including admission mRS, GCS, and ADL scores; intracerebral hemorrhage volume at both admission and discharge; and admission albumin levels." (PMID 41561342, 2025). "This current study looks to expand on our prior results and will look at the relationship between tumor necrosis factor alpha (TNFα), C-reactive protein (CRP), VEGF, Homocysteine (Hcy), and CRP to albumin ratio (CAR) in predicting outcomes and severity in spontaneous intracerebral hemorrhage." (PMID 33585095, 2021). "The negative prognostic value of an increased serum urea-to-albumin ratio on intra-hospital mortality is frequently investigated in general critically ill patients and patients with septic shock, although not in neurosurgical patients with spontaneous intracerebral hemorrhages (ICH)." (PMID 37240644, 2023). "We conducted a systematic review and meta-analysis of serum concentrations of ischaemia-modified albumin (IMA) in subjects with or without acute ischaemic stroke (AIS), intracerebral haemorrhage (ICH), and subarachnoid haemorrhage (SAH)." (PMID 35625582, 2022).
nasopharyngeal carcinoma (28 papers, 2014 to 2026). A carcinoma arising from the nasopharyngeal epithelium. "Increasing age, high number of radiation treatments, low BMI, and low albumin levels are significant nutritional risk factors in patients with nasopharyngeal carcinoma." (PMID 38832098, 2024). "A meta-analysis showed that lower ALB levels before treatment were significantly associated with poorer metastasis-free survival in nasopharyngeal carcinoma." (PMID 35663321, 2022). "Univariate and multivariate analyses indicated that N2-3 stage, serum ferritin > 300 μg/L and serum albumin < 42 g/L were independent risk factors for distant metastasis of nasopharyngeal carcinoma (P < 0.001, P = 0.013, P = 0.002, respectively)." (PMID 29069861, 2017). "Pre-albumin was a predictive marker for weight loss in nasopharyngeal carcinoma patients." (PMID 29137377, 2017). "Furthermore, low albumin levels been associated with poor outcomes in almost every primary cancer type, including colorectal, cervical, hepatocellular, gastric, lung, ovarian, and nasopharyngeal cancers." (PMID 40103850, 2025). "In this study, we aim to evaluate the significance of the prognostic nutritional index (PNI) and C-reactive protein/albumin ratio (CRP/Alb) in the prognosis of patients with locally advanced nasopharyngeal carcinoma (NPC)." (PMID 41752776, 2026). "Similar nomograms, combining TNM stage and hemoglobin–albumin–globulin ratio, have already proven prognostic value for overall and progression-free survival in nasopharyngeal carcinoma." (PMID 41303863, 2025). "A study found that the LARwas an independent prognostic indicator for patients with nasopharyngealcarcinoma, which was more predictive than using LDH or albumin and more accuratethan the current staging system for nasopharyngeal carcinoma." (PMID 39077353, 2024). "The C-reactive protein-to-albumin ratio is a proven prognostic predictor of nasopharyngeal carcinoma." (PMID 33652976, 2021). "A low serum ALB reflects a poor nutritional status and has been proven to be an independent predictor of poor survival in various cancers, including lung cancer, nasopharyngeal cancer, and breast cancer." (PMID 28654895, 2017). "Similarly, in nasopharyngeal carcinoma, the lymphocyte–ALB–neutrophil ratio served as an independent predictor of overall and progression-free survival and was incorporated into validated prognostic nomograms (C-index = 0.70)." (PMID 40740647, 2025). "Combination of higher N stage, serum ferritin and lower serum albumin levels may be valuable for predicting distant metastasis of nasopharyngeal carcinoma patients following standard intensity-modulated radiotherapy and chemotherapy." (PMID 29069861, 2017). "Low serum albumin is predictive of poor survival in nasopharyngeal carcinoma (NPC)." (PMID 24718309, 2014). "In this study, we aimed to evaluate the prognostic value of the pretreatment fibrinogen-albumin ratio index (FARI) in nasopharyngeal carcinoma (NPC) patients receiving definite radiotherapy." (PMID 37996660, 2023). "This phase I/II study aimed to determine the maximum tolerated dose (MTD) of nanoparticle albumin-bound paclitaxel (nab®-paclitaxel) plus cisplatin as treatment for metastatic nasopharyngeal carcinoma (NPC)." (PMID 27411683, 2016). "Although there is no recommended cutoff value for CRP/Albumin ratio, a value of 0.12 found in the current work is consistent with optimal cutoffs of 0.14 and 0.10 reported previously in patients with nasopharyngeal carcinoma and soft tissue sarcoma." (PMID 32181373, 2020). "Despite evidence supporting the high correlation of the novel platelet-to-albumin ratio (PAR) with survival in diverse malignancies, its prognostic relevance in nasopharyngeal carcinoma (NPC) remains underexplored." (PMID 38918690, 2024). "The C-reactive protein/albumin (CRP/Alb) ratio has been recently identified as a prognostic factor in various cancers, whereas its role remains unclear in metastatic nasopharyngeal carcinoma (NPC)." (PMID 28676731, 2017).
pressure ulcers (28 papers, 2014 to 2025). "Albumin displayed a statistically significant hazard ratio for pressure sore development, with a 1 gm/dL increase associated with a 1.15 times higher hazard ratio at a p-value of 0.001." (PMID 40565436, 2025). "Cox (2011) reported that low albumin levels and high inflammatory markers are important risk factors for pressure sore development." (PMID 40428232, 2025). "In the group of patients with pressure ulcers, the lowest values of albumin (3.20 g/dL), hemoglobin (10.81 g/dL), and nutritional risk index (NRI) (88.13 pts)." (PMID 37447196, 2023). "The positive correlations suggested that lower risk of pressure ulcers (higher score on the Braden Scale) corresponded to higher albumin and total protein values." (PMID 33669609, 2021). "Statistically significant differences were found between such variables as albumin concentration (p < 0.001) and total protein level (p = 0.007) versus pressure ulcer risk." (PMID 33669609, 2021). "Moreover, it can predict the risk of mortality, infection and pressure ulcers with more sensitivity than nutritional indicators, such as serum albumin and BMI." (PMID 35789107, 2022). "However, only albumin, haemoglobin, MAC and MAMC were associated with pressure ulcer and only albumin predicted pressure ulcer formation and mortality." (PMID 26376778, 2015). "Nevertheless serum albumin has been shown to be associated with pressure ulcers and mortality in different clinical settings, it is well accepted that the serum albumin level could be affected by a variety of factors and could represent an inflammatory marker." (PMID 26376778, 2015). "Albumin, haemoglobin and mid-arm circumference are inversely associated with pressure ulcers." (PMID 26376778, 2015). "At univariate and logistic regression analysis, mid-arm circumference (p = 0.04; beta = −0.89), mid-arm muscle circumference (p = 0.050; beta = −1.29), hemoglobin (p = 0.04, beta −1.1) and albumin (p = 0.04, beta −7.91) were inversely associated with pressure ulcers." (PMID 26376778, 2015). "The aim of this investigation was to identify the biochemical and anthropometric indexes of nutritional status associated to pressure ulcers and to verify whether albumin predicts short-term mortality in MCS patients." (PMID 26376778, 2015). "Since albumin and haemoglobin could be affected by a variety of factors, this association suggests to optimize nutrition and investigate on other mechanism leading to mortality and pressure ulcers." (PMID 26376778, 2015). "Compared to the control group, which used conventional pressure ulcer powder gauze to cover the wound surface, human albumin demonstrated a significant effect in treating pressure ulcers and was straightforward in clinical application." (PMID 41323027, 2025). "The multivariable Cox regression analysis revealed that males with a high BMI, increased systolic blood pressure, elevated albumin levels, and a more extended ICU stay were at a significantly higher risk of developing pressure ulcers (p-value < 0.05)." (PMID 40565436, 2025). "This was more prominent in the GH during the CP, in which fewer patients were admitted from nursing homes, patients were younger, and had a lower incidence of pressure ulcers and higher albumin levels, all indicators of healthier patients." (PMID 40649037, 2025). "This review showed that ONS significantly improved serum albumin levels and reduced rates of infections, pressure ulcers, and overall postoperative complications." (PMID 40869488, 2025). "We applied topical oxygen therapy combined with human albumin for dressing changes, during which the healing of pressure ulcers is assessed promptly." (PMID 41323027, 2025). "There was also an increase in potassium levels (4.14 vs. 4.48; p = 0.056) and albumin (2.8 vs. 3.3; p = 0.098), while the incidence of pressure ulcers decreased during this period." (PMID 40649037, 2025).
pressure ulcers (continued). "Patients with pressure sores had higher rates of low albumin levels (43.8 vs. 28.0%) and EN (39.2 vs. 31.1%) and a lower rate of spontaneous feeding (12.0 vs. 19.2%)." (PMID 36776614, 2023). "The area under the ROC curve for albumin to predict the pressure ulcer formation was 0.76 (SE = 0.09; p = 0.029; lower limit 0.57, higher limit 0.94)." (PMID 26376778, 2015). "The aim of this study was to investigate the association between various nutritional status parameters (in particular albumin) and pressure ulcers formation and short-term mortality in minimal conscious state patients." (PMID 26376778, 2015). "An albumin concentration equal to 3.1 g/dl achieved adequate sensitivity (72 %) to predict pressure ulcer." (PMID 26376778, 2015). "Due to the high cost of albumin, a small amount of the stock solution can be retained in the bottle after intravenous administration, allowing for its collection and subsequent use in treating pressure ulcers." (PMID 41323027, 2025). "Furthermore, they tended to have lower BMI levels and to have pressure ulcers (p=0.086 for both) and significantly lower albumin and total and HDL cholesterol levels (p<0.001, p=0.040 and p=0.039, respectively) than those surviving at follow-up." (PMID 33815869, 2021). "Furthermore, a low albumin concentration (<3.1 g/dl) predicted pressure ulcer formation as well as mortality." (PMID 26376778, 2015). "Moreover, as cBMI and albumin are closely associated with pressure ulcer development in the ICU, it is possible that mBMI may predict pressure ulcer development in the ICU, although additional studies are needed to test this hypothesis." (PMID 29652842, 2018). "Key predictors of pressure ulcer severity included prolonged ICU stay (p < 0.001), low albumin (Stage I: 3.4 ± 0.5 g/dL vs. Stage IV: 2.4 ± 0.8 g/dL; p < 0.001) and high CRP (Stage I: 28 mg/L vs. Stage IV: 142 mg/L; p < 0.001)." (PMID 40428232, 2025). "In this population we demonstrated an inverse association between some nutritional depletion indicators such as albumin and haemoglobin levels, as well as indexes of skeletal muscle wasting (represented by MAC and MACM) and pressure ulcers." (PMID 26376778, 2015).